CD4 (CD4 molecule)
Diseases named in the same sentence as CD4 in open-access papers (continued):
Sharing a sentence is not in itself a finding about the gene and the disease.
tumor (continued). "We then investigated the intratumoral infiltration of regulatory T cells (Tregs, CD3+CD4+CD25+Foxp3+) was examined by flow cytometric examination since Tregs are capable of restraining effective anti-tumor immune responses of CTLs42." (PMID 29670088, 2018). "CD4+/PD-1+ tumor-infiltrating lymphocytes had a significant relationship with Ki-67 expression whereas CD4+/PD-1− tumor-infiltrating lymphocytes had a significant relationship with E-cadherin expression." (PMID 30069490, 2018). "We observed that combined therapy increased tumor-infiltrating CD4+ (more than three times), CD8+ lymphocytes (more than eight times) as well as NK cells (more than three times) levels compared with control tumors." (PMID 29320562, 2018). "Indeed, distinct CD4 T cell receptor clonotypes were recently described to be associated with distinct states of T cell activation following tuberculosis infection or within the tumor microenvironment, suggesting that access to antigen can regulate the extent of T cell heterogeneity." (PMID 30386342, 2018). "The tumor microenvironment harbors lymphoid subpopulations, such as NK cells, B cells, CD4+ T cells, CD8+ T cells, and Tregs." (PMID 29765907, 2018). "Hexatherapy modified the tumor immune landscape by favoring effector T cells and limiting the immunosuppressive cell populations, thus improving the CD4+ T cell:Treg and CD8+:Treg ratios." (PMID 30400835, 2018). "Anergy of tumor Ag experienced CD4+ T cells has also been evoked as a mechanism of immune tolerance but its definition remained vague until recently." (PMID 29844317, 2018). "The tumor infiltrates CD4+ T cells that expressed the transcription factor of FOXP3 (FOXP3), which acts on the regulatory T (Treg) cells that impeded the effective immune response to cancer cells, show significantly worse prognosis." (PMID 29658188, 2018). "The combination of axitinib with CTLA-4 inhibitor reduced tumor growth, increased survival and increased the number of CD4+ and CD8+ T cells, intratumoral DCs and suppressive MDSCs in both the intracranial and subcutaneous models." (PMID 29515799, 2018). "These activated stromal cells, along with CD4+ T cells and myeloid-derived suppressor cells (MDSCs), are the main sources of IL-6 in most tumor microenvironments, alongside the tumor cells themselves." (PMID 30671025, 2018). "In our patient, CD4 infiltration within the tumor was similar (within the 95% CI) to that observed in post-transplant CRC and in sporadic CRC, while that observed in UC-related CRC was significantly higher." (PMID 29915171, 2018). "This treatment led to a reversal of CD4 T cell exhaustion and restored the effector functions of tumor-specific CD4 T cells." (PMID 29032503, 2018). "We also found that high tumor infiltration of CD4+ and CD8+ T lymphocytes significantly correlated with low tumor expression of SNAIL." (PMID 29732001, 2018). "Several studies describe a conversion of conventional CD4 T cells to regulatory T cells in the tumor microenvironment." (PMID 29032503, 2018). "Compared with tumour cells untreated with heat shock, hyperthermia-treated ones have sensitized dendritic cell vaccines more effective in inducing CD4+ and CD8+ T cells to participate in the anti-tumour immune response." (PMID 29386009, 2018). "CD4+ T cells participate to tumor rejection by helping CD8+ T cell priming or migration to the tumor bed, recruiting innate cells or directly killing tumor cells." (PMID 29844317, 2018). "CTCL represents a series of skin-based neoplasms of T-cell origin, predominantly comprised of peripheral CD4+ T-cells." (PMID 29915722, 2018). "We also investigated the existence of different subpopulations of T cells in xenograft tumor tissues by CD4 and CD8 staining." (PMID 30373602, 2018).
tumor (continued). "In ESCC microenvironment, significant low Foxp3+, CD4+ and CD8+ T cells were observed to correlate with improved survival of the cancer, and high tumor-infiltrating neutrophil was significantly associated with progression of the disease." (PMID 30305803, 2018). "Meanwhile, it significantly reduced Treg cells CD4+CD25+Foxp3+ in the tumor microenvironment in comparison to PBS group (6.13%, 2.32%, 5%, and 12.9%) respectively." (PMID 29959375, 2018). "In contrast, after CD4+ depletion, we observed more than three-fold reduction of the tumor mass in treated mice." (PMID 29320562, 2018). "Here, cytotoxic cluster differentiation 4 (CD4) T cells gained anti-tumor activities against multiple epitopes of the tumor and in synergy with the lytic function of VSV, resulted in higher tumor clearance." (PMID 29473868, 2018). "CD4+ T cells are critical for priming, inducing subsequent expansion and generation of memory of tumor-specific CD8+ T cells." (PMID 29755647, 2018). "Similar to others we observed a diverse effect on tumor growth after CD4+, CD8+ lymphocytes, and NK cells depletion." (PMID 29320562, 2018). "Any of the treatments (LVR01x3, CHOPx2, and CHOPx2 + LVR01x3) induced a significant increase of tumor-infiltrating CD4+ T lymphocytes and a decrease in Treg cells population as compared to untreated control (PBS)." (PMID 29410666, 2018). "This showed that the primary activation of tumor-specific CD4 T cells is locally restricted to the tumor site, rather than a systemic phenomenon." (PMID 29032503, 2018). "Both relapsed and relapse-free groups demonstrated significant potentiation of CD4+ and CD8+ T cells specific to shared tumor-associated antigens (gp-100, MART-1, NY-ESO-1)." (PMID 29973204, 2018). "IL-12-LNP treatment was associated with reduced tumor burden and increased infiltration of activated (CD44+) immune cells such as helper CD3+ CD4+ T cells into the tumor." (PMID 30458889, 2018). "Tumor-infiltrating CD4+ T cells exhibit traits of chronic exhaustion during tumor progression, accompanied by up-regulation of inhibitory receptor LAG-3." (PMID 30603054, 2018). "Depletion of host Tregs and immunization at a distant site from the tumor indicates a key role for the TdLN in which Tregs locally inhibit the priming of tumor Ag-specific naive CD4+ T cells in a dominant manner." (PMID 29844317, 2018). "Ninety-nine percent reduction of CD4+ T cells led to tumor rejection in 100% of the M7824-treated mice." (PMID 29721396, 2018). "In colon 26 animal models, injection into large primary lesions led to substantial tumor necrosis, recruitment of dendritic cells, and engagement of CD4 and CD8 T- cells." (PMID 30400822, 2018). "Histological and immunohistochemical analysis displayed that, in tumor-bearing mice administered with diosgenin, the tumor necrosis and CD4+/CD8+ T-cell infiltration increased along with an enhancement of IFN-γ expression in tumor tissues." (PMID 30305604, 2018). "By focusing on overlapping clones among tissue compartments, we revealed that a small fraction of CD8+ T cell repertoire in the dLN or PBL was enriched oligoclonally in the tumor, and that the anti-CD4 mAb treatment increased the dLN-PBL-tumor overlap." (PMID 30733724, 2018). "Regulatory T cells (Tregs) are a subpopulation of CD4+ CD25+ T lymphocytes that inhibit anti-tumor immunity by promoting immune tolerance through direct suppressive functions on T cells or by secreting immunosuppressive cytokines such as IL-10 and TGF-b." (PMID 29872507, 2018). "MLKL-mRNA treatment rapidly induces T cell responses directed against tumor neo-antigens and requires CD4+ and CD8+ T cells to prevent tumor growth." (PMID 30143632, 2018). "An example in GBM is the mutation (R132H) in the IDH1 gene, which can function as an immunogenic antigen initially recognized by CD4+ T cells, which then progressively lose their anti-tumor function." (PMID 29317703, 2018).
tumor (continued). "This was particularly evident in the RENCA model, which clearly shows decreases in all lymphocyte populations (CD8 T cells, Tregs, CD4+Foxp3-, B cells, and NK cells) with tumor progression." (PMID 30388137, 2018). "Anti-PD-1 and anti-LAG-3 synergized in the ID8-OT-I murine model to prolong survival, reduce tumor burden, and reduce Tregs, while increasing CD4+ and CD8+ TILs." (PMID 30049987, 2018). "Several studies have confirmed the helper function of tumor-specific CD4+ T cells and showed that the anti-tumor activity of combined treatment with CD4+ and CD8+ T cells is more pronounced than that seen when using individual cell types." (PMID 30214445, 2018). "This process, in conjunction with a reduced infiltration of immunosuppressive cells, and a probable predominance of CD4+ Th1 cells, effectively reduces tumor growth and promotes the establishment of immune memory." (PMID 29755647, 2018). "These cells, which are CXCR5− PD-1low, comprise ~10% of tumor CD4+ T cells, and their frequency correlates positively with plasma cell infiltrates and negatively with overall survival." (PMID 30190721, 2018). "The second effect is the interaction with naïve CD4+ T cells; upregulation of PD-L1 on the surface of tumor-derived MDSCs leads to the functional exhaustion of CD4+ effector T cells." (PMID 30619286, 2018). "We are now in the process of conducting a phase I clinical trial for a humanized anti-human CD4 depleting antibody IT1208 in Japan to promote the anti-tumor immune response in humans." (PMID 30733724, 2018). "Our study found significant hypomethylation of FOXP3-TSDR in tumor-infiltrating CD4+ T cells of CRC patients, which is consistent with the results of other investigators." (PMID 30013992, 2018). "Coculture experiments demonstrate a synergism of gene-modified CD4+ and CD8+ T cells for anti-tumor activity, which was dependent on IL-2 secretion from CD4+ T cells." (PMID 30214445, 2018). "Starting three days prior to tumor re-challenge two of the NPS-treated groups were CD4- or CD8-depleted by intra-peritoneal administration of daily doses of anti-CD4 or anti-CD8 antibody." (PMID 29324830, 2018). "Analyses via transcriptome deconvolution and immunohistochemistry showed more CD3+ and CD4+ tumor-infiltrating lymphocytes (TILs) in HL than DLBCL." (PMID 30384489, 2018). "Our study shown that less CD4+ and CD8+ T cells were found in spleen and tumor of the untreated B16-F10 tumor mice, which was associated with tumor growth." (PMID 29317734, 2018). "One issue that remains to be fully addressed is the choice of primer(s) that would appropriately stimulate both DC-mediated T-helper 1 (Th1) polarization of tumor-specific CD4+ T cell and cytotoxic CD8+ T cell (CTL) responses." (PMID 29904904, 2018). "Our data indicated that STAT5 and TET2 were significantly upregulated in tumor-infiltrating CD4+ T cells of CRC." (PMID 30013992, 2018). "Regulatory CD4 T cells (Tregs) are among the most studied suppressor cells in the tumor microenvironment and their role in mediating tumor progression has been reported in many types of cancer." (PMID 30460193, 2018). "UniTI-01 treatment increased intratumoral T cells and CD8+ T cells:CD4+ Treg ratio across different syngeneic tumor models." (PMID 30400822, 2018). "Genetic alterations leading to loss of MHC Class I, MHC Class II, and CD58 contribute to the failure of CD 8+ T lymphocyte, CD4+ lymphocyte, and NK cell-mediated tumor cytotoxicity." (PMID 30101129, 2018). "This points the fact that changes in TAMs phenotype during combined therapy resulted in enhanced tumor infiltration by CD4+, CD8+ lymphocytes and NK cells." (PMID 29320562, 2018). "PD-L1 is the primary PD-1 ligand that is up-regulated in solid tumours, where it can inhibit cytokine production and the cytolytic activity of PD-1+, tumour-infiltrating CD4+ and CD8+ T-cells." (PMID 29599916, 2018).
tumor (continued). "In conclusion, we found that CD4+ T lymphocyte tumor infiltration and PD-L1 expression on tumor cells were independent prognostic factors in eCCA." (PMID 29732001, 2018). "In the context of tumor immunity, CD4+ T helper cells aid activation of CD8+ cytotoxic lymphocytes, but can also eradicate tumors in the absence of CD8+ T cells." (PMID 30140266, 2018). "Anti-tumor immune responses, especially mediated by CD4+ T-cells, are critical for tumor cells eradication and therapies modulating those responses are appealing in a growing number of cancers." (PMID 30459932, 2018). "Taken together, the presence of CD8+PD-1+IL-7Rα−, CD4+PD-1+, and CD4+OX-40+ T cells indicates activated T cells in the tumor." (PMID 30042403, 2018). "IFNγ is a major effector cytokine produced by CD4+ T cells, which can induce tumor-killing macrophages." (PMID 30190583, 2018). "Analysis of TIL T-cell subsets across several tumor types in 2 independent sample sets revealed an expansion of CD4+CD8+ T-cell subset enriched in RCC." (PMID 30534127, 2018). "Upon the fecal transplantation from the responders, the accumulation of CXCR3+ CD4+ T cells, which is a characteristic feature of Th1, in the tumor tissues as well as the up-regulation of PD-L1 on CD4+ T cells in the spleens were observed." (PMID 30003334, 2018). "Immunological abnormalities associated with TME inhibit the priming of antitumor adaptive immunity or tolerize tumor-specific CD4+ and CD8+ T cells." (PMID 29360750, 2018). "Most of the TILs are CD8+ T cells, CD4+ helper T cells (Th), and CD4+ regulatory T cells (Tregs), as evidence suggest that TILs are predictor of tumor outcome." (PMID 30134816, 2018). "When these CD4 T cells were transferred from a cured donor host to the recipients with Her2/neu expressing tumors, these anti-tumor CD4 T cells independently facilitated tumor regression in the recipient host." (PMID 29473868, 2018). "Tumor cells can also dampen the activation and proliferation of antigen specific CD4+ TH cells and CD8+ TC cells through binding of programmed death ligand (PD-L1) to the PD-1 receptor on T cells." (PMID 30237863, 2018). "Tumor-derived exosomes also work as antigen delivery systems, capable of preventing tumor development in a CD4+ and CD8+ T cell-dependent manner." (PMID 29696022, 2018). "In animal models, antibodies to the GITR have been shown to partially deplete Treg in vivo in the tumor microenvironment and to simultaneously provide co-stimulatory signals to CD4+ and CD8+ T effector cells resulting in inhibition of tumor growth." (PMID 29868011, 2018). "Further analysis showed that LBP-treated mice had lower MFI of PD-1 on CD8+ T cells and percentage of CD4+ CD25− PD-1+ T cells in tumor tissues than those in the model group (P < 0.01)." (PMID 29967800, 2018). "In a mouse cancer model, immunotherapy promoted the anti-tumor response by enhancing infiltration, proliferation, and CD4+CD8 Teffs activity." (PMID 29707158, 2018). "PD-1 is highly expressed in tumors and a large portion of Tumor-Infiltrating Lymphocytes (TILs), consisting of both CD4+ Treg cells and CD8+ cells with resulting decreased production of cytokines." (PMID 30046565, 2018). "There are many immune effector cells such as CD8+ T cells and CD4+ T cells, and various immunosuppressive cells such as regulatory T (Treg) cells and myeloid derived suppressor cells (MDSCs) infiltrating in the tumor site." (PMID 30285868, 2018). "CD4+ TIL were stimulated with autologous tumor or dendritic cells (DC), or anti-CD3/CD28 and assayed for cytokine production by ELISA and flow cytometry." (PMID 30400835, 2018). "In line with this we found increased infiltration of PD-1+ T cells in the tumor microenvironment and reduced production of TNFα by CD4+ and CD8+ T cells in the lung of STAT1−/− mice bearing tumour." (PMID 30647851, 2018).
tumor (continued). "Depletion of CD4+ T cells or regulatory T cells (Tregs) in combination with IL PV-10 and anti-PD-1 antibody treatment resulted in an enhanced anti-tumor effect." (PMID 29694419, 2018). "In the ovarian tumor, IL-16, primarily a Th1 cytokine, has been reported to be a critical chemoattractant for the recruitment of CD4+ T cells into the tumor." (PMID 30200478, 2018). "Although CD8+ T cells have shown clinical promise, human CD4+ T cell subsets that exhibit properties of stemness and natural migration to the tumour have yet to be identified." (PMID 29996914, 2018). "The association between higher frequency of CM T cells (CD4 and CD8) and an increased tumor inflammatory profile is congruent with reports that CM T cells are the primary repository of the immunogenic experiences of a lifetime." (PMID 30123214, 2018). "CD4+ Th1 cells and CD8+ T cells associated with the release of INF-γ critically regulate the tumor immunity by killing and impending cancer growth." (PMID 29662489, 2018). "We and other groups have previously investigated the methylation status of the IFNG locus in CD4+ T cells from LNs and tumours." (PMID 30075815, 2018). "The accumulation of regulatory T cells (Tregs), a subset of CD4+ T cells, presents anti-tumor immunity to suppress effector CD8 T cells, leading to an ineffectiveness of the immune system." (PMID 30104473, 2018). "FTY720 administration successfully blocked the CP1-dependent increase in both CD8 and CD4 TILs, and, consequently, reversed the anti-tumor efficacy of CP1 + PD-1 combination therapy." (PMID 29686284, 2018). "This initial response supported DC migration and tumor antigen presentation to T CD4+ cells, stimulating adaptive immunity and cytotoxic T cell response against the tumor." (PMID 29315242, 2018). "CD4 T cells have effector functions by secreting multiple cytokines or activating other immune cells acting on immunity of tumor." (PMID 29682534, 2018). "Here, a direct killing was abolished by using an MHC class II-disparate model and clearance of tumor cells by CD4 T cells was critically reliant on IFN-γ." (PMID 29032503, 2018). "Among BC patients, CD4+/PD-1+ and CD4+/PD-1− TILs had diverse pathological features in tumor microenvironment." (PMID 30069490, 2018). "Pre-clinical models, including a model of GBM, utilizing CD4+ cells transduced with a tumor-specific CAR have been found to aid in tumor-killing by other T-cell subsets as well as to lyse tumor cells directly." (PMID 30740109, 2018). "Feature (e) quantifies the variation (also at the millimeter length scale) of the ratio of the number of CD4 T cells in the vicinity of tumor cells over the number of proliferating T cells in the vicinity of tumor cells." (PMID 30619761, 2018). "There is also evidence that PD-L1-expressing TCR gamma delta (γδ) T cells can abrogate the tumor-directed activity of CD4 and CD8 T cells, which can be reversed by immune checkpoint blockade using anti-PD-L1 antibodies." (PMID 30283732, 2018). "Taken together, occurrence of tumor-specific CD4 and CD8 T cells in tumor tissue is regarded as a good prognostic factor, but tumor immunogenicity is not a general characteristic of tumor development." (PMID 29032503, 2018). "CD4+ T lymphocytes are crucial mediators of immune responses that can play opposing functions during tumor development, with their role depending on influences within the microenvironment." (PMID 30112116, 2018). "This phenomenon has been attributed to PD-1/PD-L1 mediated induction of anergy and apoptosis of activated T cells, tumor resistance to the cytotoxic T cell response, and differentiation of CD4+ T cells into Fox3p + CD4+ Treg cells." (PMID 29769148, 2018). "Efficient anti-tumor immune responses mediated by tumor-specific CD4+ T cells have been reported by several groups, although in most instances, the underlying effector mechanisms remain poorly understood." (PMID 30083157, 2018).